JAK2 (Janus kinase 2)
Diseases named in the same sentence as JAK2 in open-access papers (continued):
Sharing a sentence is not in itself a finding about the gene and the disease.
gastric cancer (continued). "One study shows that JAK2 or STAT3 inhibitor reduces 5-FU resistance and autophagy through ATF6-mediated ER stress in gastric cancer cells, which also enhances the sensitivity of gastric cancer cells for 5-FU." (PMID 38536006, 2024). "However, the levels of p-JAK2, a key molecule upstream of p-STAT3, were higher in the gastric cancer cell lines than in the normal gastric epithelial cell line GES-1." (PMID 36672337, 2023). "In addition, some evidence has investigated that JAK2/STAT3 pathway is involved in the regulation of ferroptosis, such as gastric cancer and head and neck squamous cell carcinoma." (PMID 36814203, 2023). "Furthermore, vortioxetine hydrobromide inhibits the cell proliferation dependent on JAK2 and SRC and suppresses the growth of gastric cancer PDX model in vivo." (PMID 37147297, 2023). "Moreover, gastric cancer cells treated with palmitic acid decreased the expression of p-STAT3, p-JAK2, N-cadherin and vimentin indicating that palmitic acid inhibited the growth of gastric cancer by blocking the STAT3 signaling pathway." (PMID 37240342, 2023). "For example, miR-375 inhibited progression of hepatocellular carcinoma by targeting JAK2/STAT3 signalling pathway; miR-375 reduced the stemness of gastric cancer cells through triggering ferroptosis; miR-375 also functioned as a tumour suppressor in tongue squamous cell carcinoma." (PMID 36476264, 2023). "Furthermore, IL-17 secreted by CAFs upregulates JAK2/STAT3 signaling, which promotes gastric cancer cell malignancy." (PMID 37173977, 2023). "Additionally, the protein level of phosphor-Janus kinase 2 (JAK2) was diminished by genipin treatment, indicating that the STAT3/JAK2/Mcl-1 pathway is suppressed by genipin treatment in gastric cancer cells." (PMID 35628447, 2022). "As the cancers progress, studies have shown that the upregulation of PD-L1 was due to the activation of the Janus kinase 2/signal transducers and activators of the transcription 1 (JAK2/STAT1) signalling pathway in EC and other cancers such as colorectal, pancreatic, and gastric cancer." (PMID 36010904, 2022). "Additionally, the protein level of phospho Janus kinase 2 (JAK2) was decreased by Genipin treatment, indicating that the Stat3/JAK2/Mcl-1 pathway is suppressed by Genipin treatment in gastric cancer cells." (PMID 31351462, 2019). "Thus, inhibition of the JAK2/STAT3 signaling pathway is a crucial step for repression of invasion and EMT in gastric cancer." (PMID 29409467, 2018). "HLA-DRA, HLA-DRB5, JAK2, HLA-DQA1, HLA-DMA, CASP8, and Fas could be predictive factors for gastric cancer prognosis." (PMID 29867026, 2018). "We therefore conclude that ponicidin exhibited significant growth inhibition of gastric carcinoma cell line MKN28 and induced apoptosis of MKN28 cells via the signaling pathway regulated by Janus kinase 2 (JAK2) and signal transducers and activators of transcription 3 (STAT3)." (PMID 25588213, 2015). "Here we show that treatment of human AGS gastric cancer cells with the Janus Kinase (JAK) inhibitor WP1066 dose-, and time-dependently inhibits STAT3 phosphorylation, in conjunction with reduced JAK2 phosphorylation, reduced proliferation and increased apoptosis." (PMID 24804649, 2014). "Further studies are required to detect if the JAK2 activity and its potential relevant cytokines are more prone to male and nonsmoker with gastric cancer." (PMID 23717640, 2013). "Moreover, neutrophils enhance the migration, invasion and EMT of gastric cancer cells through the IL-17a/JAK2/STAT3 signaling, meanwhile blocking the IL-7a or disrupting the JAK2/STAT3 signaling increase the tumor cytotoxicity of neutrophils against the cancer." (PMID 38245798, 2024). "In the present study, galangin reduced the phosphorylated JAK2 and STAT3 in MGC 803 cells at 12 h, and the inhibitory effect of galangin on cell viability of MGC 803 cells was counteracted by STAT3 overexpression, indicating galangin inhibited gastric cancer in a STAT3-dependent manner." (PMID 33981228, 2021).
gastric cancer (continued). "In human gastric cancer (GC), HOXD-AS1 silencing inhibits cancer cell growth through inactivating janus kinase 2/signal transducer and activator of transcription 3 (JAK2/STAT3)." (PMID 32425696, 2020). "In gastric cancer (GC), activation of JAK2/STAT3 could promote HIF-1α/VEGFA axis, and bolsters macrophage polarization, thus facilitating GC metastasis and angiogenesis." (PMID 39130627, 2024). "Research illustrated that overexpression of ACBD3-AS1 launched accumulation of JAK2, indicating potential comic dialog between ACBD3-AS1 and the JAK2 signaling pathway, which revealed that this transcription factor could unleash tumor booster properties in gastric carcinoma." (PMID 34332535, 2021). "Here, we report on the anti-EMT effect of ATO in gastric cancer cells by demonstrating dephosphorylation of JAK2/STAT3 and modulation of EMT markers including Snail1 and E-cadherin by ATO, and suggest that SHP-1 might be an important mediator for inactivation of the JAK2/STAT3 signaling pathway." (PMID 29409467, 2018). "We further demonstrated that SCRS data amplified by either MDA or MALBAC from a gastric cancer cell line could accurately detect gastric cancer CNVs with comparable sensitivity and specificity, including amplifications of 12p11.22 (KRAS) and 9p24.1 (JAK2, CD274, and PDCD1LG2)." (PMID 26251698, 2015).
lung cancer (154 papers, 2010 to 2026). A malignant neoplasm involving the lung. "Another investigation highlighted the relationship between JAK2/JAK3 mutations in lung cancer and the expression of programmed cell death ligand-1 (PD-L1), implying potential benefits of immunotherapy for patients harboring JAK3 gene mutations." (PMID 38894865, 2024). "In particular, we focused on the effects of PA on MAPKs and JAK/STAT and showed that ERK1-2, p38, JNK, and the JAK2/STAT3 pathway are implicated in the regulation of lung cancer cell migration by PA." (PMID 37509443, 2023). "To explore the implication of JAK2 mutations in lung cancers in the context of immunotherapy, we analyzed the TCGA cohort of 515 lung adenocarcinomas with both exome sequencing and RNA-seq data available." (PMID 29082853, 2017). "Similarly, miR-210 transferred by lung cancer cell-derived exosomes acts as a proangiogenic factor in cancer-associated fibroblasts by modulating the JAK2/STAT3 pathway." (PMID 36977736, 2023). "MiR-210 has been previously linked to lung cancer through the modulation of the JAK2/STAT3 pathway." (PMID 35885958, 2022). "The significance of Janus Kinase (JAK2) mutation in lung cancer is not clearly understood." (PMID 35844327, 2022). "Interestingly, our recent work demonstrated that while IL-6 is associated with lung cancer diagnosis in both EAs30 and AAs31, the effect size was considerably larger among AAs, which is further evidence that this IL-6/JAK2/STAT3 pathway is important among AAs." (PMID 31844068, 2019). "Finally, BCAA metabolism has recently been associated with tyrosine kinase inhibitor resistance in lung cancer, suggesting such metabolic reprogramming may also contribute to the inefficacy or resistance to JAK2 inhibition." (PMID 33329600, 2020). "However, detailed mechanistic experiments will be needed to determine whether these are indeed actionable mutations, especially given a recent report that up to half of JAK2 mutations in nonsmall cell lung cancer can be inactivating." (PMID 31844068, 2019). "This study highlights the therapeutic potential of Melittin with Erlotinib in targeting the JAK2/STAT3/mTOR/PI3K pathways for A549 lung cancer treatment." (PMID 40243485, 2025). "Previous studies have identified specific CHIP mutations, such as those in TET2, JAK2 and AXSL1, as drivers of risk for diseases like acute kidney injury and lung cancer." (PMID 40679991, 2025). "In solid tumors, JAK2 signaling has an essential role in colorectal cancer, breast cancer, lung cancer, prostate cancer, and cervical cancer." (PMID 41516206, 2025). "Overall, these findings suggest that Melittin significantly enhances the activity of Erlotinib against lung cancer cell lines by modulating the JAK2/STAT3 signaling pathway." (PMID 40243485, 2025). "Another study that examined the anticancer potential of various cucurbitacin compounds in different cancer models found that CuI inhibited the activation of STAT3 and JAK2 in A549 lung cancer cells." (PMID 38397437, 2024). "In our study, we found that a microenvironment with high IL-6 expression in lung cancer was able to activate the JAK2/STAT3 pathway in TAMs, and STAT3, a transcription factor, was able to promote C/EBPβ expression." (PMID 38424624, 2024). "Ovarian cancer EV miR-630 has been found to activate NF-κB and lung cancer EV miR-210 activated the janus kinase 2/signal transducer and activator of transcription 3 (JAK2/STAT3) pathway, prompting the switch of fibroblasts to CAFs." (PMID 37978566, 2023). "In lung cancer, limited research has revealed JAK1 and JAK2 loss-of-function mutations, with JAK2 mutant cells found to be unresponsive to IFNγ treatment." (PMID 38067409, 2023). "The results showed that rhTβ4 inhibited the phosphorylation of JAK2/STAT3 proteins in lung cancer cells (A549) and lung fibroblasts (Mlg)." (PMID 36835236, 2023).
lung cancer (continued). "As a potential antitumor drug, UA was able to inhibit the enrichment of the lung CSC population by inhibiting the activation of Jak2-Stat3, in turn reversing the resistance of lung cancer cells to cisplatin." (PMID 37089712, 2023). "It is known that the activation of this pathway leads to an upregulation of various genes that are implicated in cell survival and proliferation, and we show here that PA stimulates lung cancer cell migration through the JAK2/STAT3 pathway." (PMID 37509443, 2023). "The inhibitory action of CUR on the JAK2/STAT3 pathway is implicated in the reduction of tumour spores and the suppression of tumour growth in mice bearing lung cancer xenografts." (PMID 37697969, 2023). "The results of Zhang et al27 suggested that the overexpression of miR-4443 promoted the resistance to epirubicin-based chemotherapy of non–small-cell lung cancer cells via the activation of the Janus kinase 2 (JAK2)/STAT3 pathway." (PMID 36690076, 2023). "Fibroblasts, isolated from human lung cancer tissues, were found to actively secrete IL-6 and enhance metastatic activity in human lung cancer cell lines through JAK2 and STAT3 signal transduction activation." (PMID 36986550, 2023). "Our study reports for the first time that SH2B3 regulates EMT and anoikis resistance by inhibiting JAK2/STAT3 signaling in lung cancer." (PMID 35589677, 2022). "In lung cancer, mesenchymal stem cells can enhance tumorigenesis by activating IL-6/JAK2/STAT3 pathway." (PMID 36591515, 2022). "HMA inhibits the growth of A549 lung cancer cells, which is related to the induction of apoptosis and inactivation of IL-6/JAK2/STAT3 signaling pathway." (PMID 36591515, 2022). "Consistently, here we observe that TGF-β1 activates JAK2/STAT3 signaling in lung cancer cells, and overexpression of SH2B3 inhibits this activation." (PMID 35589677, 2022). "MUC16 performs a meaningful function in metastasis and tumourigenesis in lung cancer by regulating TSPYL5 through JAK2/STAT3/GR." (PMID 36059804, 2022). "Many studies demonstrated that targeting the JAK2/STAT3 signal is an effective therapy for lung cancer metastasis." (PMID 35216134, 2022). "Research has demonstrated that abnormal JAK2/STAT3 signaling pathway activation occurs in lung cancer and other tumor tissues and tumor cells and it is engaged in the occurrence, metastasis, development, and invasion of tumors." (PMID 35789603, 2022). "Taken together, our results demonstrate that SH2B3 modulates anoikis, EMT, and proliferation, migration, and invasion of lung cancer cells by suppressing JAK2/STAT3 signaling." (PMID 35589677, 2022). "Among the five PRlncRNAs included in the signature, the lncRNA PICART1 is closely associated with the suppression of lung cancer cell proliferation by targeting the AKT1 and JAK2/STAT3 signaling pathways." (PMID 35739504, 2022). "In summary, our study is the first to illustrate the crucial roles of SH2B3 in lung cancer and reveals that TGF-β1/SH2B3 axis regulates the anoikis resistance and EMT process of lung cancer cells via JAK2/STAT3 and SHP2/Grb2/PI3K/AKT signaling pathways." (PMID 35589677, 2022). "In conclusion, SH2B3 restrained the development of anoikis resistance and EMT of lung cancer cells via suppressing JAK2/STAT3 and SHP2/Grb2/PI3K/AKT signaling cascades, leading to decreased cancer cell proliferation, migration, and invasion." (PMID 35589677, 2022). "Curcumin was found through the JAK2/STAT3 pathway to reduce tumorsphere growth in H460 lung cancer cells in in vivo and in vitro studies." (PMID 34209829, 2021). "Positive p-STAT6 staining was detected in the primary tumors of 5 out of 7 EML4-ALK-positive lung cancer patients, while p-JAK2 appeared in all seven primary tumors." (PMID 34090412, 2021). "As upstream mediator, aryl hydrocarbon receptor induces JAK2/STAT3 axis to promote lung cancer stemness." (PMID 34769099, 2021).
lung cancer (continued). "CAFs isolated from human lung cancer tissue secrete IL-6, which stimulates JAK2 and STAT3 signal transduction in human lung cancer cells, thereby increasing metastasis." (PMID 34079469, 2021). "Lung cancer cells have been shown to be susceptible to polyI:C combined with inhibitors of IL6 and JAK2/STAT3." (PMID 33562773, 2021). "PEAK1 overexpression contributes to EMT and tumour metastasis by activating ERK1/2 and JAK2 signalling in lung cancer." (PMID 32244796, 2020). "Sun and colleagues have also discovered that 2- hydroxy-3-methylanthraquinone can inhibit lung cancer cell growth and invasion by downregulating IL-6-induced JAK2/STAT3 pathways." (PMID 33299414, 2020). "Ding et al36 showed that PEAK1 activated the ERK1/2 and JAK2 signaling pathways and promoted the malignant biological behaviors of lung cancer cells." (PMID 32167655, 2020). "Our results indicate that high expression of microRNA-608 inhibits the proliferation, migration, and invasion of lung cancer cells by targeting BRD4 via the JAK2/STAT3 pathway." (PMID 31621555, 2020). "The regulation of the drug resistance of lung cancer cells by ARL4C was through activating the β-catenin/JAK2/STAT5A signaling pathway." (PMID 33194732, 2020). "FUZ is a critical regulator of cilia structure, whose expression is associated with poor prognosis in lung cancer patients; this effect of FUZ is mediated through the activation of ERK1/2 and JAK2/STAT3 signaling via the formation of the FUZ–BNIP3 complex." (PMID 31952344, 2020). "According to recent research, alterations in MET-activation and JAK2-inactivation are the independent factors that affect the response to immune checkpoint inhibitors like PD-L1 in lung cancer." (PMID 33014809, 2020). "With regard to lung cancer, the JAK2/STAT3 pathway was also found to mediate the process of cancer metastasis." (PMID 31621555, 2020). "Activation of PAF/platelet-activating factor receptor (PAFR) promotes lung cancer progression via the activation of Src/STAT3 or JAK2/STAT3." (PMID 31952344, 2020). "Previously, we reported that MUC16 is overexpressed in pancreatic, breast and lung cancer and promotes a rapid G2/M checkpoint transition through its interaction with JAK2/STAT3, leading to accelerated proliferation." (PMID 32709695, 2020). "In this study, we demonstrated that autophagy enhanced VEGFA expression of lung cancer cells via activation of JAK2/STAT3 signaling pathway both in vitro and in vivo." (PMID 30755242, 2019). "The present study is the first to illustrate that LDOC1 functions as a bridge between tobacco smoke exposure and IL-6/JAK2/STAT3 activation in lung cancer." (PMID 30634502, 2019). "Western blot results showed that JAK2 was significantly higher expressed in lung cancer cells compared with normal epithelial cell." (PMID 31754348, 2019). "Next, we investigated the role of JAK2/STAT3/VEGFA pathway in the anti-angiogenic potential of anlotinib in lung cancer cell." (PMID 30755242, 2019). "The expression of circ_ZNF124, miR-337-3p and JAK2 (Janus Kinase 2) in lung cancer cell lines and normal epithelial cells were detected by qRT-PCR (quantitative real-time PCR)." (PMID 31754348, 2019). "Curcumin exhibited its therapeutic efficiency in lung cancer treatment by means of the downregulation of NF-κB in human lung cancer cell lines A549 and also by acting on the JAK2/STAT3 signaling pathway, inhibiting JAK2 activity." (PMID 31590362, 2019). "Meanwhile, recent studies also revealed that autophagy directly regulats JAK2/STAT3 signaling pathway in lung cancer cells." (PMID 30755242, 2019). "In particular, the data revealed a novel regulatory mechanism of the IL-6/JAK2/STAT3 loop in the pathogenesis of lung cancer." (PMID 30634502, 2019). "The anti-cancer effects of ACEE in lung cancer cells are mediated at least in part by down-regulation of the JAK2/STAT3 signaling pathway." (PMID 30914735, 2019).